CCND1 (cyclin D1)
Diseases named in the same sentence as CCND1 in open-access papers (continued):
Sharing a sentence is not in itself a finding about the gene and the disease.
lung adenocarcinoma (continued). "Moreover, results of the in vivo and in vitro experiments all demonstrated that CASC9.5 promoted lung adenocarcinoma cell proliferation and metabolism by regulating the expression levels of cyclin D1, E-cadherin, N-cadherin and β-catenin." (PMID 29311567, 2018). "Furthermore, cell cycle analysis showed miR-363-3p can induce S phase arrest by downregulating Cyclin-D1 and upregulating Cyclin-dependent kinase-2 in lung adenocarcinoma cells." (PMID 28423618, 2017). "Importantly, cyclin D1, was indeed increased in A549 cells after the addition of HMC-1 exosomes, which then can be associated to increased proliferation of the lung adenocarcinoma cells." (PMID 25311367, 2014). "A signaling pathway involving EGFR, ErbB2, ErbB3, phosphatidylinositol 3-kinase (PI3K), Akt, glycogen synthase kinase 3- β (GSK3-β), and cyclin D1 is essential for the maintenance of survival, mitosis, and invasiveness of human lung adenocarcinoma cell lines as well as to evade apoptosis." (PMID 22724003, 2012). "Our study found that SH could inhibit Ki-67 and cyclin D1 protein expression in lung adenocarcinoma, promote p21 protein expression, and decrease the MCM2 protein expression levels, thus blocking tumor proliferation and inhibiting A549 cell proliferation activity." (PMID 41444284, 2025). "Furthermore, HMC-1 exosomes contain and transfer KIT protein, but not the c-KIT mRNA to A549 cells and subsequently activate KIT-SCF signal transduction, which increase cyclin D1 expression and accelerate the proliferation in the human lung adenocarcinoma cells." (PMID 25311367, 2014). "On the other hand, in lung adenocarcinoma, apelin-13 (the 13 amino acid form) induces proliferation through the activation of ERK1/2, facilitating the expression of cyclin D1 and the induction of autophagy." (PMID 36291097, 2022). "HCG18 can also act as an oncogene in lung adenocarcinoma by enhancing HMMR expression and can accelerate nasopharyngeal carcinoma progression by upregulating CCND1." (PMID 34976998, 2021). "We show that YTHDF1 deficiency inhibits NSCLC cell proliferation and xenograft tumor formation through regulating the translational efficiency of CDK2, CDK4, and cyclin D1, and that YTHDF1 depletion restrains de novo lung adenocarcinomas (ADC) progression." (PMID 31653849, 2019). "The present study found that cyclin D1 is a downstream regulatory factor of CASC9.5 and plays a role in regulating the growth of lung adenocarcinomas." (PMID 29311567, 2018). "Conversely, down-regulation of endogenous CUEDC2 significantly increased growth of lung adenocarcinoma cells by activating the PI3K-Akt singling pathway, down-regulating p21, and up-regulating cyclin D1." (PMID 26023733, 2015). "Our results demonstrated that up-regulation of CUEDC2 decreases proliferation of lung adenocarcinoma cells, by inhibiting the PI3K-Akt transduction pathway and concomitant p21 up-regulation and cyclin D1 down-regulation." (PMID 26023733, 2015). "The treatment of lung adenocarcinoma cells with DAPT decreased the baseline level of survivin and suppressed the induction of Cyclin D1 by PTE." (PMID 23671619, 2013). "Our results showed that curcumin down-regulated cyclin D1 and c-MET expression in lung adenocarcinoma xenograft tissues." (PMID 21858220, 2011).
lung adenocarcinoma (continued). "The results indicated that dried apricot polyphenols (DAPs) could cause cell cycle arrest in the G0/G1 and G2/M phases by decreasing the cyclin D1, CDK4, cyclin B1, CDK1, and CDK6 levels in A549 human lung adenocarcinoma cells." (PMID 39796398, 2025). "Several initiated signaling pathways, including linc00467/miR-20b-5p/cyclin D1 pathway and STAT1-induced upregulation of linc00467 promoted lung adenocarcinoma progression through epigenetically suppressing dickkopf WNT signaling pathway inhibitor 1 to activate Wnt/β-catenin signaling." (PMID 34713767, 2021). "Moreover, Western blot results revealed upregulation of cyclin D1 and p21 in PQM-214-treated samples, with a downregulation of cyclin B. Conclusions: PQM-214 seems to act on different molecular targets in lung adenocarcinoma cells, inhibiting cell proliferation and inducing apoptosis." (PMID 40573310, 2025). "Based on this observation, cyclin D1 may be one of the targets of vorinostat in lung adenocarcinoma cells irrespective of exposure to B[a]P." (PMID 26681199, 2015). "In lung adenocarcinoma cells, the expression of CCNE1, but not CCND1, was positively correlated with the CDCA2 levels." (PMID 35694386, 2022).
endometrial cancer (83 papers, 2000 to 2025). Primary or metastatic malignant neoplasm involving the endometrium (mucous membrane that lines the endometrial cavity). "Kaplan–Meier survival analysis demonstrated a statistically significant association between CCND1 expression and OS in the overall endometrial cancer cohort (p = 0.029)." (PMID 39940659, 2025). "Kaplan–Meier survival analysis revealed that CCND1 immunohistochemical expression, defined using a cut-off value of 1, demonstrated a potential association with OS in endometrial cancer patients." (PMID 39940659, 2025). "Aberrant overexpression of Cyclin D1 has been observed in various cancers, including endometrial cancer, and is often associated with unchecked cellular proliferation, tumor progression, and poor prognosis." (PMID 39940659, 2025). "The CCND1 gene encoding for cyclin D1 is an established oncogene amplified in a variety of tumours such as breast, lung or endometrial cancer." (PMID 32374893, 2020). "Our results are in line with two other previously published studies in which oncogenic, c-terminal cyclin D1 mutations were identified in endometrial cancer." (PMID 29969496, 2018). "CCND1 mutations in advanced or metastatic endometrial carcinomas of the MSK-IMPACT cohort (n = 15) with corresponding patient clinico-pathological characteristics and CCND1 mutation effect." (PMID 29969496, 2018). "Combined together, these data clearly demonstrate that ω-3 PUFAs can strongly suppress carcinogenesis and progression of endometrial cancer by inhibiting activation of PI3K/Akt/cyclin D1 signal pathway in the context of PTEN deficiency." (PMID 26468779, 2015). "Not only elevations in cyclin D1 protein, but also mutations that lead to such increases, have been reported in patients with endometrial cancer." (PMID 22792274, 2012). "With respect to endometrial cancer, there has been one published report on the association between the cyclin D1 870 G>A polymorphism and endometrial cancer risk in Korean women." (PMID 18822177, 2008). "Kaplan-Meier survival analysis and T-tests were used to evaluate the influence of the cyclin D1 870 G>A polymorphism on the age of diagnosis of endometrial cancer." (PMID 18822177, 2008). "A number of studies have shown that overexpression of cyclin D1 is associated with endometrial cancer and that it is an early event in tumourigenesis." (PMID 18822177, 2008). "The 870 G>A polymorphisms (rs605965) in the cyclin D1 gene was genotyped in an Australian endometrial cancer case-control population including 191 cases and 291 controls using real-time PCR analysis." (PMID 18822177, 2008). "This study focused on the 870 G>A polymorphism in cyclin D1 and its association with endometrial cancer risk." (PMID 18822177, 2008). "The focus of this study was to examine the 870 G>A polymorphism in cyclin D1 and its association with endometrial cancer risk in Caucasians including 191 endometrial cancer cases and 291 controls." (PMID 18822177, 2008). "Additionally, while the study identified significant prognostic associations of CCND1 expression in endometrial cancer, the functional mechanisms underlying these observations were not experimentally validated." (PMID 39940659, 2025). "The overexpression of CCND1 in endometrial cancer is associated with the loss of PTEN." (PMID 35409214, 2022). "The majority of CCND1-mutated endometrial cancer cases (70%, 21 of 30 endometrial cancers) contained mutations in the c-terminus of cyclin D1 that may be implicated in cyclin D1 activation and gain-of-function." (PMID 29969496, 2018). "We next interrogated the endometrial carcinoma cohort of cases from the MSK-IMPACT study in order to determine whether CCND1 c-terminal mutations also occurred in the advanced or metastatic endometrial carcinoma setting." (PMID 29969496, 2018). "Thus, elevation of ω-3 PUFAs in the uterine tissues strongly decreased PTEN-deficiency induced Akt phosphorylation and cyclin D1 expression in malignant endometrial cancer tissues." (PMID 26468779, 2015).
endometrial cancer (continued). "Notably, c-myc activity has been implicated in the etiology of endometrial carcinomas, and cyclin D1 is upregulated in endometrial carcinomas." (PMID 22792274, 2012). "Women homozygous for the variant cyclin D1 870 AA genotype showed a trend for an increased risk of developing endometrial cancer compared to those with the wild-type GG genotype, however this result was not statistically significant (OR 1.692 95% CI (0.939–3.049), p = 0.080)." (PMID 18822177, 2008). "In addition, several studies have been reported an abundance of CCND1 in endometrial carcinoma, which is hypothesized to be caused by altered protein degradation and nuclear export due to mutations present in threonine 286 of the CCND1 coding region." (PMID 23874806, 2013). "These images reflect distinct expression patterns observed in tumor samples, indicating varying levels of CCND1 in different histological subtypes of endometrial cancer." (PMID 39940659, 2025). "Although CCND1 is primarily associated with cell cycle regulation, our findings indicate that its role may extend to processes beyond proliferation control, particularly in pathways that influence tumor adaptability, immune interactions, and progression in endometrial cancer." (PMID 39940659, 2025). "Subsequently, we conducted an analysis to evaluate the impact of CCND1 mRNA expression on PFS in patients with endometrial cancer." (PMID 39940659, 2025). "Among all endometrial cancer cases, high CCND1 expression exhibited a trend toward poorer OS compared to low expression; however, this difference was not statistically significant (p = 0.12)." (PMID 39940659, 2025). "This study highlights the multifaceted role of CCND1 in endometrial cancer, suggesting its involvement in pathways beyond cell cycle regulation, including apoptosis, immune response, and tumor microenvironment modulation." (PMID 39940659, 2025). "Conversely, in the mRNA analysis, lower CCND1 expression significantly correlated with poorer survival, specifically in the endometrioid subtype of endometrial cancer (p = 0.0004)." (PMID 39940659, 2025). "Endometrial cancer (EC) harbors highly recurrent cell cycle pathway alterations, especially hyperactivation of the CCND1/CDK4/6 axis, raising the potential for use of CDK4/6 inhibitors in these cancers." (PMID 41560755, 2025). "Reactome pathway analysis was performed to explore the biological functions of genes positively correlated with CCND1 in Uterine Corpus Endometrial Carcinoma (UCEC)." (PMID 39940659, 2025). "MiR-302A-loaded UC-MSCs-Exo was reported to suppress the proliferation and migration of endometrial cancer cells by inhibiting the expression of cyclin D1 and the AKT signalling pathway during endometrial cancer treatment." (PMID 39416732, 2024). "Loss of PTEN is commonly found in endometrial cancer and hyperplasia with cell dysplasia, which reinforces that CCND1 overexpression can be used as a marker for the early development of endometrial cancer." (PMID 35409214, 2022). "CCND1 is a target of miR-142, and miR-142 inhibited proliferation of endometrial cancer cells by targeting CCND1." (PMID 34983363, 2022). "In summary, our results demonstrated that FBXL16 promoted MPA resistance of Ishikawa cell by PP2AB55α interaction and AKT1/GSK3β/cyclin D1 pathway in endometrial carcinoma, while knockdown of FBXL16 can reverse the MPA resistance of Ishikawa." (PMID 36106050, 2022). "In endometrial cancer cells, miRNA302 inhibits cell proliferation and migration, induces apoptosis, attenuates invasiveness by inhibiting cyclin D1 and CDK1, and arrests the cell cycle in the G2/M phase." (PMID 32760226, 2020). "It was reported that lncRNA ABHD11-AS138 interacted with Cyclin D1 and promoted the growth of endometrial cancer cells, but the mechanism was unclear." (PMID 33139730, 2020).
endometrial cancer (continued). "Another study provided evidence that miR-302 directly targets another cyclin family member, Cyclin D1, and suppresses its expression, contributing to delayed tumorigenicity of endometrial cancer cells." (PMID 32792866, 2020). "The overexpressed Cyclin D1 has been shown to play oncogenic role in endometrial carcinoma and was related to diagnosis, prognosis, and survival of patients." (PMID 32670874, 2020). "Cyclin D1 plays an important role in LSD1-regulated estrogen-induced endometrial cancer cell proliferation." (PMID 30846786, 2019). "This group also verified the positive correlation between LSD1 and cyclin D1 in endometrial cancer tissues by immunohistochemistry." (PMID 30846786, 2019). "Specific CCND1 c-terminal mutations involving Thr286 and Pro287 have been previously reported in endometrial cancer, such as T286I, P287T, P287S, which resulted in nuclear accumulation of cyclin D1, gain-of-function and cellular transformation." (PMID 29969496, 2018). "MiRNA-302 inhibits the tumorigenicity of endometrial cancer cells by suppressing cyclin D1 and CDK1." (PMID 30326936, 2018). "Overexpression of lncRNA ABHD11‐AS1 increased the tumorigenicity and up‐regulated cyclin D1 in an in vivo model of endometrial cancer in nude mice." (PMID 29799152, 2018). "In preclinical models, palbociclib or knockout of cyclin D1 had therapeutic potential against endometrial cancer cell lines and xenografts expressing the retinoblastoma protein, Rb." (PMID 29969496, 2018). "In endometrial cancer, the majority of CCND1 mutations were located in the carboxy-terminal region of cyclin D1 (70%, 21 of 30 endometrial cancers), likely resulting in cyclin D1 oncogenic activation of cyclin D1-CDK4/6 complexes and gain of function." (PMID 29969496, 2018). "In conclusion, this study reveals ABHD11‐AS1 is up‐regulated and promotes tumorigenesis in endometrial carcinoma by positively targeting cyclin D1." (PMID 29799152, 2018). "LncRNA ABHD11‐AS1 functions as an oncogene to promote cell proliferation and invasion in endometrial carcinoma by positively targeting cyclin D1." (PMID 29799152, 2018). "This positive feedback loop promotes endometrial cancer cell proliferation by increasing cyclin D1 expression and altering cell cycle progression." (PMID 28978098, 2017). "We also demonstrated decreased proliferation in endometrial cancer cells after Pak1 knockdown along with reduced cyclin D1 expression." (PMID 26218748, 2015). "Overexpression of cyclin D1, a D-type cyclin regulating G1-S phase cell cycle progression, has been reported in endometrial cancer." (PMID 26218748, 2015). "Compared with previously published reports of c-myc and cyclin D1 expression frequencies in other tumors, such as endometrial carcinoma, these detection frequencies (47.8% (22/46) c-myc-positive and 52.2% (24/46) cyclin D1-positive) are low." (PMID 24942472, 2014). "Consistent with interaction of E2 and PKCα mitogenic signaling pathways, we previously demonstrated that PKCα activates the cyclin D1 promoter in endometrial cancer cells." (PMID 23843797, 2013). "Lef1 is overexpressed in both mouse and human endometrial cancer specimens, and certain Lef1 downstream targets are activated through this mechanism, specifically cyclin D1 and MMP7." (PMID 22792274, 2012). "We next examined expression of the Lef1 target cyclin D1 in the developing mouse uterus because cyclin D1 levels are elevated in patients with endometrial carcinoma." (PMID 22792274, 2012).